KPNA2 (karyopherin subunit alpha 2)
Diseases named in the same sentence as KPNA2 in open-access papers (continued):
Sharing a sentence is not in itself a finding about the gene and the disease.
breast carcinoma (continued). "In breast cancer, both RBM15 and karyopherin subunit alpha 2 (KPNA2) are significantly overexpressed in tissues and cell lines." (PMID 41403702, 2025). "We identified components of a cytonuclear transport system, including importins KPNA2 and KPNB1, as well as a subunit of the NPC RANBP2, as binding partners of ARID1B in breast cancer cells." (PMID 40671262, 2025). "In breast cancer, studies show that FOXM1 directly regulates KPNA2 as a target gene, while KPNA2 reciprocally facilitates FOXM1’s nuclear transport, creating a regulatory loop that influences tumor progression." (PMID 40002266, 2025). "As a nuclear transport protein, KPNA2 is involved in the cytoplasmic retention of key DNA damage response proteins including BRCA1, RAD51, and CHK1 in breast cancer cells." (PMID 40002266, 2025). "In conclusion, the findings suggest that KPNA2 and FOXM1 play a crucial role in breast cancer progression by positively correlating with key genes involved in cell cycle regulation and molecular subtypes." (PMID 40002266, 2025). "This intricate interplay between KPNA2 and the FOXM1-CCNB1/B2 axis not only provides insights into breast cancer cell cycle regulation but also suggests potential therapeutic targets in breast cancer treatment." (PMID 40002266, 2025). "USP1 interacts with KPNA2, and deubiquitination of KPNA2 is a key factor in USP1 promoting metastasis; therefore, USP1 inhibition can markedly reduce the migration of breast cancer cells." (PMID 36357365, 2022). "Exposure to radiation upregulated KPNA2 expression in human colorectal cancer HT29 and HCT116 cells and breast carcinoma MDA-MB-231 cells together with the increased expression of DNA repair protein BRCA1." (PMID 31212646, 2019). "Other notable breast cancer related genes identified by super-delta include YBX1, KPNA2, SKP2, and NAT1." (PMID 29268715, 2017). "The mTOR inhibitors and mTOR knockdown reduced the protein and mRNA levels of KPNA2 in NSCLC and breast cancer cells." (PMID 27009856, 2016). "Studies have indicated that aberrant KPNA2 expression can be found in early lesions, such as ductal carcinoma in situ (DSIS) in breast cancer and non-invasive bladder cancer samples." (PMID 26626145, 2015). "The expression of miR-26a and miR-26b in human breast cancer cells suppressed cell growth, at least partly through repression of CHD1, GREB1 and KPNA2." (PMID 24735615, 2014). "In breast cancer tissues and cells, both RBM15 and KPNA2 are highly expressed." (PMID 41403702, 2025). "Silencing miR-144-3p or overexpressing KPNA2 could reverse the inhibitory effect of LINC00461 silencing on cell invasion and migration in breast cancer." (PMID 32355466, 2020). "Notably, HR+/HER2- breast cancer patients with high KPNA2 but low FOXM1 mRNA levels showed significantly better survival outcomes (OS: p = 0.0355; DSS: p = 0.0424), suggesting a novel prognostic signature for this major breast cancer subtype." (PMID 40002266, 2025). "High KPNA2 levels serve as an independent prognostic factor, correlating with shorter overall survival (OS) and event-free survival (EFS) in HER2-positive breast cancer patients, regardless of treatment intensity." (PMID 40002266, 2025). "What’s more, aberrant KPNA2 expression has been found in early lesions, such as non-invasive bladder cancer and ductal carcinoma in situ (DCIS) in the breast cancer samples." (PMID 30115078, 2018). "Since USP1-mediated deubiquitination of KPNA2 contributes to tumorigenesis, researchers have found that inhibitors of USP1 such as pimozide and ML323 decrease breast cancer metastasis without showing obvious cytotoxicity in mice, offering a novel therapeutic target to be explored in the future." (PMID 34575114, 2021).
hepatocellular carcinoma (28 papers, 2012 to 2026). A malignant tumor that arises from hepatocytes. "In individuals with liver cancer, STMN1 expression was significantly correlated with E2F1/TFPD1 and KPNA2 expression and was associated with poor prognosis in patients with hepatocellular carcinoma." (PMID 36127700, 2022). "In conclusion, this study provided systematic evidence that KPNA2 was an essential factor promoting hepatocellular carcinoma and unraveled potential molecular pathways and networks underlying KPNA2-induced hepatocellular carcinogenesis." (PMID 28422734, 2017). "In summary, with in vitro and in vivo experiments, causal relationship between KPNA2 upregulation and hepatocellular carcinoma progression was more convincing in this study." (PMID 28422734, 2017). "This dual role suggests that KPNA2 is a key gene involved not only in telomere maintenance within hepatocellular carcinoma (HCC) cells but also in significantly influencing patient prognosis." (PMID 40665355, 2025). "Accordingly, the MYH9 circular product has recently been reported to play a similar role in cancer cells’ fate by increasing the mRNA stability of Karyopherin α2 (KPNA2), another known oncogene in hepatocellular carcinoma." (PMID 36900344, 2023). "KPNA2 over-expression has been correlated with poor patient outcomes in a number of malignancies including glioblastoma, colon, hepatocellular carcinoma, ovarian and breast cancers." (PMID 35948941, 2022). "In line with our observations, KPNA2, DTL, BACE2 and DTYMK were previously found to be associated with tumour stage also in other cancers, including hepatocellular carcinoma or glioma." (PMID 36320118, 2022). "CDK1, also co-expressed with KPNA2, promotes G2/M cell cycle transition and has previously been reported in hepatocellular carcinomas." (PMID 35948941, 2022). "Dysregulation and prognostic roles of Karyopherin α2 (KPNA2) were reported in many malignancies including hepatocellular carcinoma (HCC)." (PMID 34616632, 2021). "Karyopherinα2 (KPNA2) has been validated to be elevated in various cancers, including cervical carcinoma, esophageal cancer, lung cancer and hepatocellular carcinoma." (PMID 32355466, 2020). "It has been shown that TFDP1, together with E2F1, is involved in regulating hepatocellular carcinoma cells through a knockdown experiment that confirmed a physical interaction of KPNA2 with E2F1 and TFDP1." (PMID 33124660, 2020). "Since TET1-CD can induce genome-wide DNA demethylation, it is possible that oncogenes such as C-myc, Bmi1, EMS1, Kpna2 and c-fos in hepatocellular carcinoma epigenetics are also activated so as to weaken TET1-CD anticancer activity." (PMID 30551127, 2018). "Results show that KPNA2 knockdown inhibited the proliferation and growth of hepatocellular carcinoma cells in vitro and in vivo." (PMID 28422734, 2017). "Karyopherin α2 (KPNA2), involved in nucleocytoplasmic transport, has been reported to be upregulated in hepatocellular carcinoma and considered as a biomarker for poor prognosis." (PMID 28422734, 2017). "It was demonstrated as above that KPNA2 knockdown led to impaired cell growth and colony formation in human hepatocellular carcinoma HepG2 and SMMC-7721 cells." (PMID 28422734, 2017). "Here, we chose a lentivirus-mediated short-hairpin RNA (shRNA) strategy to inhibit human KPNA2 expression in two human hepatocellular carcinoma cell lines, HepG2 and SMMC-7721, to explore the impact of KPNA2 on cell growth and survival in vitro." (PMID 28422734, 2017). "The impact of KPNA2 knockdown on cell growth of human hepatocellular carcinoma was further examined using the MTT assay." (PMID 28422734, 2017). "KPNA2 knockdown also inhibited colony formation ability, induced cell cycle arrest and cellular apoptosis in two hepatocellular carcinoma cell lines, HepG2 and SMMC-7721." (PMID 28422734, 2017).
hepatocellular carcinoma (continued). "In hepatocellular carcinoma, it has been reported by different groups that KPNA2 expression is significantly higher in tumor regions than in the adjacent no-tumorous regions." (PMID 28422734, 2017). "Our study examine the roles and related molecular mechanisms of KPNA2 in hepatocellular carcinoma development." (PMID 28422734, 2017). "Thus, it is quite possible that KPNA2 knockdown interfered with the normal functions of multiple cross-linked pathways essential for cell proliferation and survival, leading to the obvious cell proliferation blockade and elevated apoptosis in hepatocellular carcinoma cells." (PMID 28422734, 2017). "Taken together, these results provide reliable evidence that KPNA2 is critically involved in hepatocellular carcinoma." (PMID 28422734, 2017). "It was shown that silencing KPNA2 expression significantly inhibited cell proliferation and colony formation while inducing cell cycle arrest and apoptosis in both hepatocellular carcinoma cell lines." (PMID 28422734, 2017). "Furthermore, KPNA2 has been reported to facilitate hepatocellular carcinoma malignancy by mediating KDM4A‐SA1‐induced activation of the AKT pathway." (PMID 40830912, 2025). "KPNA2 is supposed to inhibit apoptosis in order to promote growth and survival of tumour cells as silencing of KPNA2 induced apoptosis in breast and bladder cancer cells as well as hepatocellular carcinoma cells, respectively." (PMID 30323892, 2018). "Elevated KPNA2 expression has been observed in various cancer types, including hepatocellular carcinoma, and its expression level has been positively correlated with diagnosis in hepatocellular carcinoma." (PMID 28422734, 2017). "Initially, we analyzed KPNA2 expression status in 50 paired hepatocellular carcinoma samples from TCGA database, and showed that KPNA2 expression at the mRNA level was shown to be significantly upregulated in hepatocellular carcinoma tissues as compared to adjacent normal tissues." (PMID 28422734, 2017). "Similar to our findings, the nuclear import of PLAG1 has been illustrated to be aided by KPNA2 in hepatocellular carcinoma (HCC) and PLAG1 seemed to be partly responsible for the functional role of KPNA2 in HCC." (PMID 33731128, 2021). "The pro-tumor effects of KPNA2 have also been validated in hepatocellular carcinoma (HCC) where KPNA2 mediates the nuclear import of the transcriptional factor pleomorphic adenoma gene 1 (PLAG1) protein." (PMID 33731128, 2021). "Karyopherin α2 (KPNA2) was reported to be overexpressed and have unfavorable prognostic effects in many malignancies including hepatocellular carcinoma (HCC)." (PMID 33193737, 2020). "Experiments in hepatocellular cell lines HepG2 and SMMC-7721 indicated that KPNA2 is critical for the tumorigenesis of hepatocellular carcinoma cells in vitro, and we then wondered whether KPNA2 was important for the tumorigenicity of hepatocellular carcinoma cells in vivo." (PMID 28422734, 2017). "However, the roles of KPNA2 in tumorigenesis have not been explored comprehensively, and it has only been shown that cell proliferation and invasion are impaired in hepatocellular carcinoma cells in vitro by KPNA2 knockdown, and in vivo roles of KPNA2 have remained to be determined." (PMID 28422734, 2017). "Furthermore, recent work identified KPNA2 as a potential prognostic marker for the progression of prostate cancer, non-muscle-invasive bladder cancer, as well as non-small cell lung cancer, hepatocellular carcinoma." (PMID 22962582, 2012). "To further investigate the functional role of KPNA2 in telomere maintenance and HCC progression, we conducted KPNA2 knockdown and overexpression experiments in Hep3B hepatocellular carcinoma cells." (PMID 40665355, 2025).
hepatocellular carcinoma (continued). "Upon reviewing the literature, it is evident that CCNB2 expression in hepatocellular carcinoma (HCC) demonstrates a significant correlation with KPNA2, implicating its involvement in mitotic and cell cycle regulatory processes, thereby exerting a substantial impact on HCC progression." (PMID 39100078, 2024). "It was shown in two human hepatocellular carcinoma cell lines, HepG2 and SMMC-7721, that KPNA2 knockdown led to delayed cell proliferation, which was in consistent with previous report." (PMID 28422734, 2017).
bladder cancer (20 papers, 2014 to 2025). "For example, overexpression of KPNA2 is linked with poor survival in bladder cancer." (PMID 34650978, 2021). "This further emphasizes the role of miR-26b-5p in inhibiting bladder cancer progression by suppressing KPNA2 levels." (PMID 39956902, 2025). "KPNA2 (karyopherin subunit alpha 2), as a nuclear import protein, shows increased expression in bladder cancer TDEVs and can induce fibroblast transformation into cancer-associated fibroblasts (CAFs), suggesting its utility as a novel tumor biomarker." (PMID 41459253, 2025). "The high protein expression of OCT4 and KPNA2 were independent prognostic predictors of bladder cancer." (PMID 37627900, 2023). "The protein expression level of OCT4 was found to be positively correlated with KPNA2 expression level in bladder cancer tissues." (PMID 37627900, 2023). "The silencing of OCT4 and KPNA2 decreased bladder cancer cell proliferation and migration while increasing apoptosis." (PMID 37627900, 2023). "Here, we report that KPNA2 and OCT4 protein levels are frequently increased in bladder cancer clinical tissues and bladder cell line and associated with bladder cancer clinic-pathological parameters." (PMID 27611951, 2016). "In summary, our data indicates that the aberrant expression of KPNA2 is associated with a poor prognosis and provides the first evidence that KPNA2 contributes to OCT4 nuclear transportation in bladder cancer." (PMID 27611951, 2016). "Here, we found that expression levels of KPNA2 and OCT4 are up-regulated in bladder cancer tissues and significantly associated with primary tumor stage and bladder cancer patients' poorer prognosis." (PMID 27611951, 2016). "Our data also showed decreased cell proliferation and migration rates of bladder cancer cell lines when the expression of KPNA2 and OCT4 was silenced." (PMID 27611951, 2016). "The follow-up data of bladder patients is insufficient to conclude an explicit relationship between the expression level of KPNA2 and prognosis about bladder cancer patients." (PMID 27611951, 2016). "Both OCT4 and KPNA2 were also found to be upregulated in bladder cancer J82 and T24 cells." (PMID 37627900, 2023). "In addition, the knockdown of KPNA2 inhibits the nuclear translocation of OCT4, thus suggesting that the process of OCT4 nuclear transportation in bladder cancer was regulated by KPNA2." (PMID 37627900, 2023). "And KPNA2 was co-expressed with SMARCC1 in cell nucleus of bladder cancer." (PMID 35669562, 2022). "Additionally, KPNA2 is a pivotal predictor in the development and progression in bladder cancer patients." (PMID 27611951, 2016). "Moreover, the effect of KPNA2 on cell proliferation, apoptosis and migration of bladder cancer cell lines has been analyzed." (PMID 27611951, 2016). "Among the 195 bladder cancer samples, interestingly, the IHC results showed that the KPNA2 protein was mainly detected in the cell nucleus, with few positive immunostaining areas in cytoplasm, while the OCT4 protein were primarily expressed in cytoplasmic of cancer cells." (PMID 27611951, 2016). "However, the mechanism of KPNA2 in the development of bladder cancer is still unknown and needed to be further studied." (PMID 27611951, 2016). "Also, we propose that KPNA2 regulates the process of OCT4 nuclear transportation in bladder cancer." (PMID 27611951, 2016). "From the perspective of the direct targeting of molecules, it has been demonstrated that the inhibition KPNA2 (e.g., via the PRDM1/c-FOS pathway) has antitumor effects in bladder cancer models." (PMID 41413918, 2025). "CDK4, KPNA2, PFDN5, HSP90B1, and ZNF121 were identified as prognostic differential genes in bladder cancer." (PMID 37433010, 2023). "In detail, it has been reported that the overexpression level of KPNA2 and its cargo protein OCT4 in bladder cancer tissues were significantly related with poor prognosis of patients." (PMID 33728352, 2021).
bladder cancer (continued). "The results confirmed that both KPNA2 and OCT4 can promote cell proliferation and inhibit cell apoptosis in bladder cancer cells in vitro." (PMID 27611951, 2016). "Taken these results together, we found that the high expression of KPNA2 and OCT4 were independent prognostic predictors for bladder cancer patients." (PMID 27611951, 2016). "Our present study is the first report to illustrate the interaction between KPNA2 and OCT4 in bladder cancer." (PMID 27611951, 2016). "The protein expression of KPNA2 and OCT4 were detected by using the immunohistochemistry(IHC) in a total of 195 bladder cancer clinical tissues." (PMID 27611951, 2016). "Moreover, KPNA2 and OCT4 silencing resulted in decreased cell migration ability and proliferation rate and promoted cell apoptosis in bladder cancer cell lines." (PMID 27611951, 2016). "Thus, we confirmed that up-regulated KPNA2 and OCT4 expression is a common feature of bladder cancer that is correlated with increased aggressive tumor behavior." (PMID 27611951, 2016). "To confirm the knockdown efficiency of the specific siRNAs, we first detected the endogenic expression level of KPNA2 and OCT4 in bladder cancer cell lines J82, T24, 5637, UM-UC-3 and human uroepithelial cell line SV-HUC-1 through RT-qPCR and Western-blot analysis." (PMID 27611951, 2016). "Also, we confirmed that up-regulated KPNA2 and OCT4 expression is a common feature of bladder cancer that is correlated with increased aggressive tumor behavior." (PMID 27611951, 2016). "We determined whether KPNA2 and OCT4 influence proliferation in bladder cancer cells." (PMID 27611951, 2016). "We found that the KPNA2 and OCT4 were expressed in most of the bladder cancer tissues (total no.=195), and that KPNA2 is predominantly a nuclear protein and their expression levels were significantly correlated with clinicopathologic characteristics and highly associated with poor prognosis." (PMID 27611951, 2016). "However, the physiological roles of KPNA2 and the interaction between KPNA2 and OCT4 in bladder cancer cells has not been investigated to date." (PMID 27611951, 2016).